RGS2 (regulator of G protein signaling 2)
Diseases named in the same sentence as RGS2 in open-access papers (continued):
Sharing a sentence is not in itself a finding about the gene and the disease.
diabetes (3 papers, 2014 to 2021). "Hence, increased levels of RGS2 is a feature associated with poorly controlled type 2 diabetes mellitus." (PMID 33562475, 2021). "Understanding how RGS2 is associated with diabetes could become this protein into a new therapeutic target for those patients with hard to control glycemia." (PMID 33562475, 2021). "Remarkably, the platelet RGS2 expression levels were higher in type 2 diabetes mellitus (T2DM) patients than in healthy donors." (PMID 33562475, 2021). "Elucidation of the roles of RGS2 in regulating pancreatic β-cell mass will likely lead to a better understanding and, potentially, to novel therapies for treatment of diabetes." (PMID 28542139, 2017). "It appears then that young T2DM with high RGS2 levels have poorly controlled diabetes." (PMID 33562475, 2021). "Nevertheless, this T2DM exploratory PCA study, together with the observation that RGS2 overexpression decreases insulin signaling in HUVEC-CS cells, supports the need for studying how RGS2 relates to diabetes in humans." (PMID 33562475, 2021). "Although it is not new that high HDL levels have an inverse correlation with diabetes, we did not expect that age was inversely correlating with the RGS2 level in T2DM patients based on the RGS2 knockout mice model." (PMID 33562475, 2021).
renal fibrosis (3 papers, 2015 to 2022). A final common manifestation of a wide variety of chronic kidney diseases characterized by glomerulosclerosis and tubulointerstitial fibrosis. "RGS2 deficiency results in increased vasoconstrictor signaling in renal arteries and acceleration of renal fibrosis induced by ureteral obstruction." (PMID 26193676, 2015). "Using a rodent model of unilateral ureteral obstruction (UUO), which can simulate progressive renal fibrosis, RGS2 was shown to beneficially slow the progression of kidney fibrosis." (PMID 26300785, 2015). "This study provides evidence that RGS2 attenuated the onset of renal fibrosis in part by accelerating the deactivation of the angiotensin type 1 receptor (AT1R)-mediated signaling of the pro-fibrogenic and inflammatory systems." (PMID 26300785, 2015).
Sepsis (3 papers, 2016 to 2022). Sepsis is defined as life-threatening organ dysfunction caused by a dysregulated host response to infection. "Five genes (NKG7, SPTA1, FGL2, RGS2, and IFI27) have been proved to be potential biomarkers for sepsis-induced ARDS and exert crucial roles in the occurrence and development of sepsis." (PMID 36299685, 2022). "In summary, our study identified five key genes including NKG7, SPTA1, FGL2, RGS2, and IFI27, which were closely related to the sepsis-induced ARDS development." (PMID 34393665, 2021). "Furthermore, five genes including NKG7, SPTA1, FGL2, RGS2 and IFI27 exhibited significant differences between the sepsis-induced ARDS samples and the samples with sepsis alone in two datasets, suggesting that these five genes might be key genes that led to sepsis patients complicated with ARDS." (PMID 34393665, 2021). "Moreover, five genes including NKG7, SPTA1, FGL2, RGS2, and IFI27 exhibited notable difference between the sepsis-induced ARDS group and the control group with sepsis alone in two datasets, suggesting that these five genes might be key genes that led to sepsis patients complicated with ARDS." (PMID 34393665, 2021).
airway hyperresponsiveness (2 papers, 2017 to 2021). "Compared to wild type animals, Rgs2-/- mice showed airways hyperresponsiveness (increased airways resistance and reduced compliance)." (PMID 28107494, 2017). "Furthermore, there was less RGS2 in miR-210 inhibited ASMCs, which has been shown to be protective against the development of airway inflammation and airway hyperresponsiveness (AHR)." (PMID 34295265, 2021).
astrocytoma (2 papers, 2015 to 2020). "We measured the expression of RGS-2,-3, and -4 in both transformed glia cells (human U373 MG astrocytoma cells) and in primary rat astrocyte cultures stimulated with adenosine agonists." (PMID 26263491, 2015). "In astrocytoma cells adenosine agonists elicited an increase in RGS-2 expression solely mediated by A2B receptors." (PMID 26263491, 2015). "The present work shows that in U373 astrocytoma cells adenosine agonists up-regulate RGS2 mRNA expression and down-regulate expression of RGS3 and RGS4." (PMID 26263491, 2015). "Similarly, RGS2 has been implicated in OS, and a time- and concentration-dependent upregulation in RGS2 mRNA has been observed in human astrocytoma 1321N1 cells treated with H2O2." (PMID 33343808, 2020). "Incubation with the non-selective adenosine receptor agonist NECA leads to up-regulation of expression of RGS2 mRNA and down-regulation of RGS3 in astrocytes, similar to its effects in astrocytoma cells." (PMID 26263491, 2015). "Incubation with the non-selective adenosine receptor agonist NECA leads to up-regulation of expression of RGS2 mRNA and down-regulation of RGS3 and RGS4 in U373 astrocytoma cells." (PMID 26263491, 2015). "The effects of adenosine agonists on RGS-2, -3, -4 expression in cultured astrocytes differ in several aspects from those in U373MG astrocytoma cells." (PMID 26263491, 2015).
atherosclerosis (2 papers, 2014 to 2025). A disease characterized by the build-up of fatty material and calcium deposition in the arterial wall resulting in partial or complete occlusion of the arterial lumen. "In our study, homozygosity for the A-638-G RGS2 polymorphism was present relatively frequently—in above 50 % of cases, which could potentially be a therapeutic indication in HT treatment and atherosclerosis development." (PMID 24562335, 2014).
breast tumors (2 papers, 2007 to 2012). "Remarkably, RGS2 is over-expressed in the majority of breast cancer cell lines and primary breast tumours." (PMID 18067675, 2007). "Notably, RGS2 expression (primarily upregulated by the KR receptor) is over-expressed in the basal/myoepithelial compartment and substantially elevated in a majority of breast tumors." (PMID 22697792, 2012). "RGS2 and OXTR expression levels were not correlated in breast cancer, suggesting that RGS2 modulates a different GPCR pathway(s) in breast tumours." (PMID 18067675, 2007).
endothelial dysfunction (2 papers, 2012 to 2016). In vascular diseases, endothelial dysfunction is a systemic pathological state of the endothelium (the inner lining of blood vessels) and can be broadly defined as an imbalance between vasodilating and vasoconstricting substances produced by (or acting on) the endothelium. "Endothelium-specific deletion of RGS2 caused endothelial dysfunction with impaired EDHF-dependent vasodilatation." (PMID 23285140, 2012).
Hyperglycemia (2 papers, 2017 to 2021). An increased concentration of glucose in the blood. "Remarkably, we have found that the amount of RGS2 protein from platelets correlates with uncontrolled hyperglycemia in type II diabetic patients, particularly those at a young age." (PMID 33562475, 2021).
Insulin resistance (2 papers, 2021 to 2022). Increased resistance towards insulin, that is, diminished effectiveness of insulin in reducing blood glucose levels. "In this way, RGS2 can also be a component of the PA-induced ER stress response that we previously found associated with insulin resistance in HUVEC-CS cells." (PMID 33562475, 2021). "For this reason, in the present study, we examined the association between RGS2 expression and insulin resistance state." (PMID 33562475, 2021). "The upregulation of RGS2 protein expression is observed in HUVEC-CS cells that develop insulin resistance." (PMID 36497154, 2022). "As we show here, there is a clear correlation between insulin resistance and increased levels of RGS2 under the conditions of a high-fat diet." (PMID 33562475, 2021). "On the one hand, RGS2 could be indirectly involved in insulin resistance through the regulation of lipid metabolism." (PMID 36497154, 2022). "However, to date, there is no experimental indication of a direct relationship between changes in the expression or activity of RGS2 with insulin resistance." (PMID 33562475, 2021). "Moreover, it has been shown that thiazolidinediones, which decrease insulin resistance, reduce RGS2 expression." (PMID 33562475, 2021). "Since PA increased RGS2 expression, we decided to determine whether RGS2 overexpression without PA induces insulin resistance." (PMID 33562475, 2021).
insulinoma (2 papers, 2017 to 2024). "To determine whether RGS2 has a role in β-cell apoptosis, we compared hypoxia-induced (1% O2) cell death in the presence or absence of RGS2 gene expression in an insulinoma cell line, βTC3 cells." (PMID 28542139, 2017).
lung carcinoma (2 papers, 2022 to 2024). "In mammals, a high expressional level of RGS2 has been discovered in both gastric and lung cancer cells and is related to high malignancy and poor prognosis." (PMID 38539794, 2024).
melanoma (2 papers, 2022 to 2024). A malignant, usually aggressive tumor composed of atypical, neoplastic melanocytes. "RGS2 inhibits melanoma cell growth by inhibiting MAPK and AKT, but this effect depends on the genetic structure of the overall cell." (PMID 35992780, 2022). "RGS2 inhibits the growth of melanoma cells by inhibiting MAPK and AKT." (PMID 35992780, 2022).
metastatic disease (2 papers, 2014 to 2022). "To evaluate mRNA expression in HGSOC tumor cells precisely, we analyzed RGS2 mRNA expression in silico on the single-cell level in three publicly available HGSOC data sets that included data of therapy-naïve patients, patients with neoadjuvant chemotherapy and patients with metastatic disease." (PMID 36230542, 2022).
neuroblastoma (2 papers, 2020 to 2023). Neuroblastoma (NB) is the most common solid, extracranial childhood tumor. "Further, RGS2 modulates the activity and internalization of the dopamine D2 receptor in neuroblastoma cells, and has been implicated in dopamine receptor signaling during amphetamine self-administration." (PMID 33115496, 2020). "As previously shown in vitro, RGS2 negatively modulates the D2R-mediated Gαi/o protein signaling in neuroblastoma N2A cells." (PMID 36983013, 2023).
schizophrenia (2 papers, 2013 to 2021). A major psychotic disorder characterized by abnormalities in the perception or expression of reality. "Other studies suggested that polymorphic loci in RGS2 seem to predict the severity of schizophrenia symptoms, or they can be associated with the risk of extrapyramidal symptoms induced by typical neuroleptics-haloperidol." (PMID 34658840, 2021). "PRKG1 also interacts with RGS2 and GABRR1, which have shown modest association with schizophrenia symptoms and schizoaffective disorder, respectively." (PMID 23922650, 2013).
Anosmia (1 paper, 2022). An inability to perceive odors. "COVID-19 associated anosmia is significantly more prevalent in young females, which are the demographic group with the highest RGS2 blood expression." (PMID 36143181, 2022). "Our findings therefore suggest that the elevated RGS2 expression in SARS-CoV-2 positive nasopharyngeal cells is implicated in the common anosmia or reduced olfaction observed in many COVID-19 patients." (PMID 36143181, 2022). "We present additional evidence for a correlation for higher RGS2 expression in populations with increased risk of COVID-19-induced anosmia." (PMID 36143181, 2022). "Consistent with our hypothesis, we postulate that the reduced immunogenicity of the Omicron variant leads to a significantly milder initial immune response and in turn, milder induction of RGS2 expression and thus reduced risk of anosmia." (PMID 36143181, 2022). "Anosmia is most common among milder COVID-19 cases, which are also characterized as having higher levels of blood RGS2 expression compared to more severe patients." (PMID 36143181, 2022). "We hypothesized that anosmia in COVID-19 may also reflect SARS-CoV-2 infection-driven elevated expression of regulator of G protein signaling 2 (RGS2), a key regulator of odorant receptors, thereby silencing their signaling." (PMID 36143181, 2022).
Atrophy (1 paper, 2024). Any weakening or degeneration, especially through lack of use. "RGS2 expression was reported to be increased in the stomach of patients with atrophy or severe gastritis." (PMID 39594230, 2024).
blood pressure (1 paper, 2009). "Experimenting in mice, the team of heart expertsfirst established that after a week of induced high blood pressure,the hearts of animals engineered to lack RGS2, or regulatorof G–protein signaling 2, quickly expanded in weight by 90percent." (PMID 20108753, 2009).
Candida infection (1 paper, 2011). "Our observation that the C5aR−/− mice recapitulate the cardiac phenotype characterized by reactivation of the fetal gene expression, Rgs2 down-regulation and sensitivity to Candida infection and isoproterenol administration, reveals the first step in the mechanism of the C5 effect." (PMID 21829669, 2011).
cerebrovascular diseases (1 paper, 2024). "Research interest in RGS2 extends beyond cancer to include implications in cardiovascular and cerebrovascular diseases." (PMID 39642114, 2024).
chronic kidney disease (1 paper, 2018). Impairment of the renal function secondary to chronic kidney damage persisting for three or more months. "Also, in a mouse model of chronic kidney disease, RGS2 deficiency results in enhanced fibrogenic and inflammatory response." (PMID 29621314, 2018).
corneal diseases (1 paper, 2025). "Two genes (Rgs2 and Galnt9) were involved in pathways related to human corneal diseases, including cGMP-PKG signaling, mucin-type O-glycan biosynthesis, and oxytocin signaling." (PMID 40323269, 2025).
Corneal opacity (1 paper, 2025). A reduction of corneal clarity. "It is known that DED can result in corneal epithelial opacity; therefore, Rgs2 knockout and subsequent phenotypic corneal opacity could also be explained through this relationship." (PMID 40323269, 2025).
COVID-19 (1 paper, 2022). A disease caused by infection with severe acute respiratory syndrome coronavirus 2. "The expression of RGS2 correlated with multiple genes many of which were associated with the immune signaling and inflammation observed in COVID-19." (PMID 36143181, 2022). "Here, we present findings from analysis of RNA-sequencing data from nasopharyngeal samples, which show higher RGS2 mRNA levels in COVID-19 patients." (PMID 36143181, 2022). "Our findings on higher RGS2 mRNA levels in nasopharyngeal samples from COVID-19 patients compared with controls are based on data mining of published NCBI GEO datasets." (PMID 36143181, 2022). "Further studies of COVID-19 animal models are required for clarifying the cellular mechanisms by which SARS-CoV-2 infection drives higher expression of RGS2 mRNA." (PMID 36143181, 2022). "As a regulator of numerous G-protein coupled receptors, RGS2 may drive further neurological symptoms of COVID-19." (PMID 36143181, 2022). "We hypothesize that the olfactory dysfunction in COVID-19 may additionally reflect an infection-driven upregulation of RGS2 (regulator of G protein signaling 2), a key regulator of nasal cavity G protein-coupled odorant receptors, whose signaling is diminished by the RGS2 protein." (PMID 36143181, 2022). "The highly correlated expression of RGS2 with CXCL8, PTGS2, NAMPT, ILB1 and further inflammatory genes in COVID-19 positive nasopharyngeal swabs suggests the involvement of a common regulator, which might explain the distinct classes of COVID-19 symptoms." (PMID 36143181, 2022). "As a regulator of several G-protein coupled receptors, the elevated expression of RGS2 may drive further neurological symptoms observed in COVID-19 patients, sometimes lingering beyond negative SARS-CoV-2 PCR test findings." (PMID 36143181, 2022).
fibrosis (1 paper, 2015). the formation of excess fibrous connective tissue in an organ or tissue in a reparative or reactive process. "Without altering the magnitude of renal vascular myogenic response in RGS2-/- mice, renal perivascular fibrosis could also contribute to decreased sensitivity due to increased stiffness of the extracellular matrix of the vessel wall." (PMID 26193676, 2015).
generalized anxiety disorder (1 paper, 2019). An anxiety disorder characterized by excessive and difficult-to-control worry about a number of life situations. "Human genetic association studies linking RGS2 polymorphisms to panic disorder, generalized anxiety disorder, social anxiety disorder, and post-traumatic stress disorder." (PMID 31633064, 2019).
Gitelman syndrome (1 paper, 2014). Gitelman syndrome (GS), also referred to as familial hypokalemia-hypomagnesemia, is characterized by hypokalemic metabolic alkalosis in combination with significant hypomagnesemia and low urinary calcium excretion. "In hypertensive patients, a reduction in RGS2 mRNA and protein level was observed compared with normotensive subjects, but hypotensive patients (Bartter’s/Gitelman’s syndrome) showed an increase of the RGS2 expression." (PMID 25031678, 2014).
glaucoma (1 paper, 2009). Increased pressure in the eyeball due to obstruction of the outflow of aqueous humor. "Since glaucoma is an age-related disease, we used 12- to 15-month-old RGS2−/− and wild-type mice to evaluate the chronic effects of RGS2 deficiency on retinal ganglion cell count using tissue cryosections derived from the central and peripheral retina." (PMID 19262744, 2009). "Therefore, in future studies, analysis of RGS2 expression in the CM and TM tissues of glaucomatous and age-matched normal eyes might provide significant insight into the role of RGS2 in the pathophysiology of glaucoma." (PMID 19262744, 2009).
intracerebral hemorrhage (1 paper, 2021). A cerebrovascular disorder characterized by bleeding into one or both cerebral hemispheres including the basal ganglia and the cerebral cortex. "Our previous study showed that RGS2 expression was upregulated and relieved inflammatory injury in a collagenase-induced intracerebral hemorrhage model." (PMID 34848837, 2021). "Furthermore, our research provided novel insights into the NLRC4 inflammasome after intracerebral hemorrhage and suggested the role of RGS2 in NLRC4 inflammasome activation by LRRK2 after ICH." (PMID 34848837, 2021).
invasive carcinoma (1 paper, 2023). A carcinoma that is not confined to the epithelium, and has spread to the surrounding stroma. "In breast-invasive carcinoma of no special type (BIC-NST), the downregulation of RGS2 was associated with a significantly poorer overall survival rate." (PMID 37999477, 2023).
ischemia (1 paper, 2020). A hypoperfusion of the BLOOD through an organ or tissue caused by a PATHOLOGIC CONSTRICTION or obstruction of its BLOOD VESSELS, or an absence of BLOOD CIRCULATION. "Ischemia-induced growth arrest of astrocytes can be overridden by inhibition of regulator of G protein signaling 2 (RGS2) and treatment with cytokine erythropoietin (EPO), and cytokine-mediated induction of astrocyte survival early post-ischemia may contribute to neuroprotective effect." (PMID 32859229, 2020).
myopia (1 paper, 2019). "We have found hypermethylation of Regulator of G-protein signaling 2 (RGS2), which was earlier reported to be upregulated in the sclera of form deprivation myopia (FDM)." (PMID 30858441, 2019).
nicotine addiction (1 paper, 2021). "Moreover, individuals carrying specific RGS2 polymorphic variants may experience differential affective responses to smoking tobacco, which could make them vulnerable to developing nicotine addiction." (PMID 34658840, 2021).